C1orf141 (chromosome 1 open reading frame 141)
Tractability: PROTAC: ubiquitination databases record sites on it.
Safety:
Unwanted effects reported when the protein is acted on. In parentheses: how it was acted on, where the effect was seen, and who reports it.
Adenoma (source: ClinPGx)
Gene: Protein-coding gene on chromosome 1 (67,092,165 to 67,231,853, reverse strand). Ensembl gene ENSG00000203963.
Subcellular location (Human Protein Atlas): Intermediate filaments
Genetic constraint (gnomAD): Loss-of-function variants: 6 observed, 4.74 expected, observed/expected ratio (o/e) 1.27, 90% interval 0.66 to 1.89. That is too few expected variants to judge how well the gene tolerates losing a copy. Missense variants: 265 observed, 268.02 expected, observed/expected ratio (o/e) 0.99, 90% interval 0.89 to 1.1. Synonymous variants: 84 observed, 88.42 expected, observed/expected ratio (o/e) 0.95, 90% interval 0.8 to 1.14.
Homologues: Orthologues: chimpanzee C1H1orf141 (98% identical), macaque C1H1orf141 (92% identical), dog C1orf141 (60% identical), rabbit C1orf141 (58% identical), pig C1orf141 (54% identical), rat C5h1orf141 (38% identical), mouse 4921539E11Rik (37% identical).
Diseases named in the same sentence as C1orf141 in open-access papers:
C1orf141 is named in the same sentence as 8 diseases in open-access papers, as found by Europe PMC text mining. Sharing a sentence is not in itself a finding about the gene and the disease. The quoted sentences say what the papers report.
psoriasis (3 papers, 2015 to 2020). An autoimmune condition characterized by red, well-delineated plaques with silvery scales that are usually on the extensor surfaces and scalp. "It has been recently shown that C1orf141 is a susceptibility variant in psoriasis, a chronic inflammatory hyperproliferative cutaneous disease." (PMID 32117227, 2020). "C1orf141 is involved in psoriasis; however, its function remains to be elucidated." (PMID 32437414, 2020). "In addition, four new susceptibility genes (C1orf141, GPR160, CCDC129 and AP5B1) with unknown functions in the pathogenesis of psoriasis were also identified, indicating that additional molecular mechanisms contribute to the risk of developing psoriasis." (PMID 25854761, 2015).
sarcoidosis (1 paper, 2020). Sarcoidosis is a multisystemic disorder of unknown cause characterized by the formation of immune granulomas in involved organs. "The recent Immunochip study showed that rs12069782 in C1orf141 was strongly associated with sarcoidosis in German and Swedish populations, but not in Czech or African-American populations." (PMID 32826979, 2020).
uveitis (1 paper, 2021). An inflammatory process affecting a part of or the entire uvea. "Genome-wide association studies (GWASs) have provided a powerful tool for the genome-wide analysis of genetic susceptibility to uveitis, revealing several genes associated with uveitis, including IL23R/C1ORF141, STAT4, and ADO/ZNF365/Egr2." (PMID 34869347, 2021).
cancer (1 paper, 2014). A tumor composed of atypical neoplastic, often pleomorphic cells that invade other tissues. "Only C8orf74 exhibited no measurable expression in cancer cells / tissues (although C1orf141, HEATR7B and SATL1 could not be analysed via meta-analyses due to their absence on the arrays)." (PMID 25594029, 2014).
C1orf141 also shares sentences with these, for which no sentence is quoted: VKH disease (2 papers); autoimmune (1); prostate carcinoma (1); vitiligo (1).